KRTAP19-7 (keratin associated protein 19-7)
Description:
In the hair cortex, hair keratin intermediate filaments are embedded in an interfilamentous matrix, consisting of hair keratin-associated proteins (KRTAP), which are essential for the formation of a rigid and resistant hair shaft through their extensive disulfide bond cross-linking with abundant cysteine residues of hair keratins. The matrix proteins include the high-sulfur and high-glycine-tyrosine keratins.
Synonyms: KAP19.7
Tractability: No criterion of Open Targets' tractability assessment is met for any kind of drug.
Gene: Protein-coding gene on chromosome 21 (30,560,875 to 30,561,314, reverse strand). Ensembl gene ENSG00000244362.
Pathways (Reactome):
Developmental Biology: Keratinization
Gene Ontology:
Molecular function: protein binding
Cellular component: cytosol
Genetic constraint (gnomAD): Loss-of-function variants: 5 observed, 2.66 expected, observed/expected ratio (o/e) 1.88, 90% interval 0.8 to 1.95. That is too few expected variants to judge how well the gene tolerates losing a copy. Missense variants: 76 observed, 83.1 expected, observed/expected ratio (o/e) 0.91, 90% interval 0.76 to 1.11. Synonymous variants: 38 observed, 32.93 expected, observed/expected ratio (o/e) 1.15, 90% interval 0.89 to 1.51.
Diseases named in the same sentence as KRTAP19-7 in open-access papers:
KRTAP19-7 is named in the same sentence as 1 disease in open-access papers, as found by Europe PMC text mining. Sharing a sentence is not in itself a finding about the gene and the disease.
KRTAP19-7 shares sentences with these, for which no sentence is quoted: colorectal adenoma (1 paper).